KRT19 (keratin 19)
Diseases named in the same sentence as KRT19 in open-access papers (continued):
Sharing a sentence is not in itself a finding about the gene and the disease.
cancer (continued). "In our study, high expression of both KRT15 and KRT19 in low-risk ERG fusion negative patients was associated with the enrichment of common cancer-associated gene signatures, especially KRAS." (PMID 36033462, 2022). "In addition, we also found that the estrogen response was correlated with cancer cell differentiation and cancer stemness, marked by KRT19, in CCA, which deserves further investigation." (PMID 35664769, 2022). "Recently, liquid biopsy has been used to identify cancer patients based on KRT19 expression." (PMID 33442422, 2021). "It is a fragment of cytokeratin 19 which is produced during the differentiation of cancer cells." (PMID 31218849, 2020). "Cancer cells were stained with cytokeratin 19 (CK19), CD44, and ALDH1A1." (PMID 32155897, 2020). "KRT19+/Lgr5− cells may be cancer-initiating and radioresistant, making them functionally distinct from the radiosensitive Lgr5+ ISC population." (PMID 30999572, 2019). "Additionally, RNA sequencing data from the TCGA database showed upregulation of KRT19 mRNA expression in several cancer types." (PMID 30650643, 2019). "Next, we checked Notch signaling in both cancer cells upon KRT19 silencing." (PMID 30650643, 2019). "Although there were no changes in the amino acid sequence, it also may bias the role of KRT19 in various cancers." (PMID 30650643, 2019). "Moreover, several studies have shown the contradictory effects of KRT19 in controlling cancer progression, depending on expression patterns and cell types." (PMID 30650643, 2019). "In several cancers, KRT19 is overexpressed and may play a crucial role in tumorigenic transformation." (PMID 29747452, 2018). "Herein, we have aimed to distinctly identify the role of KRT19 in cancer stem cell reprogramming." (PMID 29747452, 2018). "In addition, we demonstrated that the overexpression or knockdown of KRT19 regulated cancer stem cell reprogramming by modulating the expression of cancer stem cell markers (ALDH1, CXCR4, and CD133) as well as the level of p-Src and p-GSK3β (Tyr216)." (PMID 29747452, 2018). "Therefore, we investigated the role of KRT19 in cancer stem cell reprogramming and drug sensitivity by the overexpression and knockdown of KRT19 in KU-CSLCs (konkuk university-cancer stem cell-like cell) and MDA-MB231 cells." (PMID 29747452, 2018). "The KRT19 expression is reported to be correlated with cancer progression and prognosis." (PMID 29747452, 2018). "Moreover, the silencing of KRT19 augmented cell migration and drug-resistance of MDA-MB231, which means that the low expression of KRT19 produced an aggressive phenotype in cancer cells, as previously reported." (PMID 29747452, 2018). "Here, we have hypothesized that KRT19 may have cancer regulating role through the reprogramming of cancer stem cell by partially modulating stemness, metastasis, and drug-resistant properties." (PMID 29747452, 2018). "As KRT19 is involved in cancer regulation through signaling pathway, as we reported somewhere." (PMID 29747452, 2018). "KRT19, a cytokeratin protein, is reported to be differentially expressed in several cancers." (PMID 29747452, 2018). "Hence, the function of KRT19 in cancer stem cell reprogramming and the drug-resistance pathway is remarkable, and it would be interesting to explore the underlying mechanisms in detail." (PMID 29747452, 2018). "This difference in sensitivity may be due to differences in the relative expression levels of KRT19 in different cancers." (PMID 26700817, 2016). "However, an alternative explanation for these two discordances could be the heterogeneous expression of cytokeratin 19 (CK19), as previously reported, which varies according to the degree of cancer dedifferentiation." (PMID 39769252, 2024). "As cancer vaccines, mRNA encoding cytokines, such as Interleukin-12 (IL-12), IL-27, IL-23, IL-36γ, and INF-α; antigens, such as OX40L, OVA, cytokeratin 19 (CK19), and MUC1; or antibodies that block immune checkpoints, such as anti-PD-1 and anti-PD-L1, can be used." (PMID 39407665, 2024).
cancer (continued). "Cytokeratin-19 (CK19) is expressed by cancer cells and may be used as a marker of metastases in GC." (PMID 37240178, 2023). "In addition, as an epithelial cytoskeleton marker, cytokeratin 19 (CK19) may serve as a prognostic indicator for cancer patients, but there are few relative studies in the context of CRC." (PMID 37400750, 2023). "Furthermore, KLK4–7 regulate gene expression of other cancer-related factors: simultaneous overexpression of these four KLKs lead, e.g., to a distinct up-regulation of moesin and keratin 19 mRNA and protein expression, while keratin 7 is strongly down-regulated." (PMID 31307411, 2019). "However, further study may elucidate the function of KRT19 in key regulatory pathways upon cancer reprogramming and drug sensitivity in various cancer stem cells." (PMID 29747452, 2018). "Therefore, our data may imply that the modulation of KRT19 expression could be involved in cancer stem cell reprogramming and drug sensitivity, which might have clinical implications for cancer or cancer stem cell treatment." (PMID 29747452, 2018). "Moreover, we revealed that the knockdown of KRT19 in MDA-MB231 cells led to an enhancement of cancer properties, such as cell proliferation, sphere formation, migration, and drug resistance, while the overexpression of KRT19 in KU-CSLCs resulted in the significant attenuation of cancer properties." (PMID 29747452, 2018). "Cancer stem cell-related markers, CD44, ABCG2, BMI1, and KRT19, expression in subclusters from trajectory, indicated enhanced self-renewal capacity in SRGN-high malignant cells." (PMID 40384866, 2025). "In particular, clusters 9, 10, 12, 13, 14, 16, 18, 19, 21, 26, 27, 28, 30, 34 and 35 not only expressed ductal cell markers (KRT19, MMP7, TSPAN8, SOX9 and LCN2), but also expressed cancer cell markers (MUC1 and PROM1)." (PMID 40362181, 2025). "The OSNA assay employs specialized gene amplification devices and reagents to amplify and detect cytokeratin 19 (CK19) mRNA in solubilized lymph nodes, enabling the identification of cancer metastasis." (PMID 40507235, 2025). "OSNA is a molecular technique that allows the detection of mRNA of cytokeratin 19 (CK19), an epithelial membrane protein found in some tumors and used as a biomarker of LN metastases in different types of cancer." (PMID 39769252, 2024). "Intriguingly, we also found that the cancer stem cells (CSC) score, calculated using common CSC markers (EPCAM, CD24, KRT19, SOX9, PROM1, CD44, THY1, CD47), was significantly higher in the EMT-subtype." (PMID 39095854, 2024). "A retrospective case-control study was conducted to develop a cancer screening test based on the detection of stromal and epithelial biomarkers (COL1A2 and KRT19) in plasma." (PMID 39273514, 2024). "The cytokeratin 19 fragment (CYFRA 21-1) is predominantly found in squamous and simple epithelial cells, and its expression is significantly increased in malignant tumors." (PMID 38828358, 2024). "Keratin 19 has a role in cancer cell proliferation and angiogenesis and its inhibition in HCC results in the control of cancer cell growth." (PMID 37726886, 2023). "Epithelial biomolecules such as cytokeratin 19 (KRT19) and carcinoembryonic antigen (CEA) are involved in cancer progression." (PMID 36834987, 2023). "Upregulation was observed in many genes, including CAV2, FGFBP1, KRT19, MST1R, OCLN, and RGS2, which play important roles in the negative regulation of EMT and metastasis phenotypes in many cancers." (PMID 37298519, 2023). "Several KRT genes, including the phylogenetically older KRT8, KRT18, KRT19, KRT23, KRT79, KRT80 and KRT222, were found to be differentially expressed in diverse types of cancers." (PMID 36949761, 2023). "Network analysis of upregulated genes revealed their enrichment in signatures of cancer cell growth and fetal liver (e.g., AFP, DLK, EPCAM and KRT19)." (PMID 37173882, 2023).
cancer (continued). "We detected cancer cells using markers typical of LUAD and alveolar epithelium (EPCAM, CDH1, KRT19, KRT18, KRT8)." (PMID 37745301, 2023). "Several members of the KRT gene family, including the evolutionarily older KRT8, KRT18, KRT19, KRT23, KRT79, KRT80 and KRT222, were shown to be differentially regulated in diverse cancer types." (PMID 36949761, 2023). "KRT19, CEA, COL1A2, and COL11A1 expression levels were much higher in cancer patients (KRT19 = 66.04 ± 14.29-fold; CEA = 245.81 ± 84.63-fold; COL11A1 = 47.80 ± 7.51-fold; COL1A2 = 40.64 ± 6.00-fold)." (PMID 36834987, 2023). "We chose keratin 19, histone H3, vimentin, and cytochrome c oxidase subunit 4 (COX IV) as target proteins, as they are related to cancers and used as cancer markers." (PMID 35513404, 2022). "Tumors also were formed by Krt19-edited PDA cells that had been rescued by expressing ectopic KRT19, and the cancer cells had regained the capacity to form the CXCL12–KRT19 coating and exclude T cells." (PMID 35046049, 2022). "In the 178 PC patients, the LAMB3, FN1, KRT17, KRT19, and ANXA1 were also upregulated in cancer tissue, compared with adjacent tissues and normal tissues." (PMID 35428170, 2022). "The quantitative molecular diagnosis of cytokeratin-19 (CK19) and carcinoembryonic antigen (CEA) that target cancer cells in axillary seroma showed that they are a predictor of locoregional recurrence in mastectomized BC patients." (PMID 36479071, 2022). "The metastases formed with PDA cells expressing both KRT19 and TGM2 exhibited the CXCL12–KRT19 coating, and cancer cell nests excluded T cells." (PMID 35046049, 2022). "KRT15, KRT19 and KRT8 were amplified and the expression were significiantly higher in the AA cancer cell lines compared to EA cell lines." (PMID 36033462, 2022). "Then, we analyzed the upregulated top five differentially expressed genes between the paracancer tissue and the cancer tissue, which included LAMB3, FN1, KRT17, KRT19, and ANXA1." (PMID 35428170, 2022). "We also discovered profound changes in the DNA methylation landscape over the promoter region of the cytokeratin-19 (KRT19), a coding gene whose CGI was almost fully methylated in normal but exhibited minimal methylation in cancer." (PMID 34732768, 2021). "As a proof of concept, we targeted loci in healthy donor DNA, including a highly variable hexanucleotide repeat in C9orf72, and four cancer-related genes with guide RNAs previously validated for PCR-free targeted sequencing (GSTP1, KRT19, GPX1, SLC12A4)." (PMID 33830997, 2021). "KRT19, FKBP10, GSK3B, and SPANXB1 have been investigated at the single-cell level in 9, 10, 16 and 3 types of cancer, respectively." (PMID 35096583, 2021). "Recently, single‐cell analysis of the transcriptome and epigenome also showed that KRT8, KRT18, CLDN4, KRT19, KRT20, etc. are highly expressed in CRCs,[12a] consistent with our results that these genes were highly expressed in cancer EPCs." (PMID 33898197, 2021). "Except for those 14 cancer classification marker genes, there were significant differences in the expression of three genes: GLI1 (GLI family zinc finger 1), KRT19 (Keratin 19), and VEGFA." (PMID 33692941, 2020). "Although the gene expression level was not statistically meaningful, the detection rates of the three cancer-related genes (AR, AR-V7, and PSMA) were higher with the CTC-μChip, while two genes (KRT19 and CD45) had the same detection rate." (PMID 32961814, 2020). "Among the KRTs, KRT19 was significantly (p < 0.001) overexpressed in both colon (COAD) and breast (BRIC) cancers compared to that in normal tissues." (PMID 30650643, 2019). "We have shown that knock-down of HUGL1 in human mammary epithelial cells leads to upregulation of five transcripts that have been linked to cancer stem cells, side population (SP) cells, or increased invasion in cancers (ABCG2, MMP2, ESR1, THBS1 and KRT19)." (PMID 29361610, 2018).
cancer (continued). "Additional cancer stem cell populations have been characterized in human epidermal SCC, including keratin 19, aldehyde dehydrogenase 1, Oct4, and Bmi1." (PMID 29113290, 2017). "Subpopulation B consisted of 121 cells (29.1%) and showed overexpression of 13 genes, including seven cancer genes (HSPB1, ANXA1, SLPI, KRT8, KRT19, KLK7, and ABL2) and several Keratin genes (KRT8, KRT7, KRT19, and KRT6B)." (PMID 28794488, 2017). "Tests for blood-fluid tumor markers are widely employed in cancer diagnosis, and several cancer biomarkers, including carcinoembryonic antigen (CEA), cytokeratin 19 fragment (CYFRA21-1), and neuron-specific enolase (NSE), are used to diagnose lung cancer." (PMID 27999202, 2017). "We found that the cancer epithelial cell markers EPCAM and cytokeratin 19 (KRT19) were highly correlated in 79 HCCs (R=0.87)." (PMID 27191501, 2016). "The epithelial and cancer cells showed higher KRT8, KRT18, KRT19 and ANXA4 expression." (PMID 39149248, 2024). "Therefore, keratins are used as commercially available markers to diagnose cancer: TPS (KRT18), TPACYK (KRT8/18) and CYFRA 21-1 (KRT19)." (PMID 36949761, 2023). "Indeed, SKBR3 cancer cells cultured in serum-free medium stained with fluorochrome-conjugated antibodies to CXCL12 and KRT19 and had formed the CXCL12–KRT19 heterodimer." (PMID 35046049, 2022). "Cancer cells in tumors containing control, scrambled small guide (sgScramble) PDA cells demonstrated staining with fluorochrome-conjugated antibodies to KRT20, KRT19, and CXCL12, respectively, and CD3+ T cells were infrequent in the areas of the KRT20+ cancer cells." (PMID 35046049, 2022). "KRT19 (AUC = 0.855, CI = 0.825 - 0.885) and FKBP10 (AUC = 0.836, CI = 0.808 - 0.864) had a certain accuracy in predicting cancer and normal, and the predictive abilities of GSK3B (AUC = 0.654, CI = 0.613 - 0.696) and SPANXB1 (AUC = 0.682, CI = 0.650 - 0.714) were less accurate." (PMID 35096583, 2021). "Common markers in both COVID-19 and cancer are carbohydrate antigens (CA) 125 and 153, carcinoembryonic antigens (CEA), human epididymis protein 4 (HE4), C-reactive protein (CRP), and cytokeratin-19 fragment (CYFRA21-1); these markers are increased in both COVID-19 and cancer." (PMID 33912588, 2021). "Furthermore, a recent study showed that PDAC excludes T cells and resists inhibitors of PD-1 checkpoints when cancer cells are coated with covalent heterodimers of CXCL12 and keratin 19 (KRT19) formed by transglutaminase-2 (TGM2)." (PMID 35008248, 2021). "Thus, further studies are necessary to uncover the effect of β-catenin phosphorylation and RAC1 activation in differential KRT19/β-catenin/NUMB-mediated regulation of Notch signaling crosstalk and contiguous regulation of cancer properties." (PMID 30650643, 2019). "Based on cell surface marker profiles and KRT14/KRT19 expression patterns in sh-UNC5A cells, we propose that the gradual loss of UNC5A results in cancer cells acquiring hybrid phenotype without expressing classic markers of EMT." (PMID 29720215, 2018). "Although KRT19 regulates EGR1/PTEN/AKT, β-catenin/NUMB/NOTCH, and HER2/ERK/SP1 cascades, we focused on the AKT, GSK3β, ERK, Src, and JNK signaling pathway in this study, as these signaling pathways are crucially involved in cancer progression." (PMID 29747452, 2018). "In the top 50 differentially expressed genes between cancer and normal tissues, three genes: neurotensin (NTS, red arrow), keratin 19 (KRT19) and matrix metallopeptidase 12 (MMP12) were screened out for their high expression in 2 cancer samples (c-13426 and c-13732)." (PMID 23418512, 2013).
cancer (continued). "further found that cancer cells could restrict T-cell motility and suppress the intratumoral accumulation of T cells by assembling a transglutaminase-2 (TGM2)-dependent filamentous coating of CXCL12-keratin-19 (KRT19) heterodimers." (PMID 37359565, 2023). "Since these two cell lines externalized KRT8 and KRT19, and the fetal calf serum in which they were cultured contained CXCL12, we determined whether the CXCL12–KRT19 coating could be formed in vitro by these cancer cells." (PMID 35046049, 2022). "This is supported by our results, showing no cytokeratin 19 detected in any of the non-cancer EVs." (PMID 34359613, 2021). "Therefore, the use of COL1A2 in combination with the KRT19 marker could contribute to the diagnosis of various types of cancer, regardless of stage." (PMID 39273514, 2024). "CEA: carcinoembryonic antigen; CYFRA: cytokeratin 19 fragment; Pro-GRP: pro-gastrin-releasing peptide.*Paratracheal lymph nodes were enlarged but confirmed negative.**Second cancer (adenocarcinoma) was detected.***Lung tumor appeared." (PMID 40698218, 2025). "After 2 weeks, mice developed carcinomas resembling HCC with the expression of hepatocyte nuclear factor-4α (HNF4α) that lacked glandular structures and keratin 19 (KRT19) expression typical for CCAs." (PMID 39948437, 2025). "Cytokeratin 19, an intermediate filament expressed by HSC-3 cancer cells, was uniformly expressed in H10 spheroids, but not in H5M5 spheroids after 24 h co-culturing." (PMID 38951897, 2024). "In the present study, we found that BIO induced the expression of the cancer stem cell markers EpCAM, CD44, KRT19, and MYC above the levels seen in MeBIO controls without inducing cytotoxicity." (PMID 30177680, 2018). "Western blot analysis confirmed that CLA carcinomas were Vimentin (VIM) positive, KRT19/CDH1 negative, while CLB carcinomas were VIM negative, KRT19/CDH1 positive." (PMID 26158412, 2015). "Importantly, the fact that we did not detect any mRNA of cancer‐specific genes (AZGP1 and KRT19), nor of CAF‐specific genes (LUM and DCN), confirmed the absence of non‐endothelial RNA contamination." (PMID 40348600, 2025). "KRT19, CEACAM5, EPCAM, DSG3, SFTPA, SFTPC and SFTPB mRNA levels were initially validated by real-time reverse transcription PCR-based quantification in 16 NSCLC tumors and 22 LNs and 12 PB samples from individuals without known cancer." (PMID 23671585, 2013). "Keratin 19, an intermediate filament protein responsible for the structural integrity of epithelial cells as a gene, frequently demonstrated promoter methylation in sporadic RCC but not in normal kidney tissue from RCC patients and non-cancer patients." (PMID 18195710, 2008).
adenocarcinoma (50 papers, 2008 to 2025). A common cancer characterized by the presence of malignant glandular cells. "She had a liver biopsy of the hepatic lesion, which revealed an adenocarcinoma with expression of cytokeratin 19, cytokeratin 7, N-cadherin, and high expression of carbonic anydrase IX." (PMID 39330010, 2024). "Liver biopsies revealed an adenocarcinoma with expression of cytokeratin 19, cytokeratin 7, N-cadherin, and high expression of carbonic anydrase IX." (PMID 39330010, 2024). "For example, keratins KRT8, KRT18, and KRT19 are expressed in most adenocarcinomas." (PMID 35267493, 2022). "However, further studies are required to fully understand whether adenosine deaminase and cytokeratin 19 fragments play the same important role in epithelial differentiation in metastatic pleural fluids from adenocarcinomas." (PMID 29854023, 2018).